SP1 (Sp1 transcription factor)
Diseases named in the same sentence as SP1 in open-access papers (continued):
Sharing a sentence is not in itself a finding about the gene and the disease.
pancreatic cancer (continued). "We examined the binding of bacteriologically expressed GST-NFATc2 to Sp1 that had been overexpressed in the pancreatic carcinoma cell lines PaTu 8988t by transfection." (PMID 28774282, 2017). "Consistently, there was also report that Celecoxib inhibits VEGF expression and reduces angiogenesis and metastasis of pancreatic cancer via the suppression of Sp1." (PMID 27713167, 2016). "We also observed that tumor growth in mice bearing L3.6pL pancreatic cancer cells depleted of Sp1 or Sp1, Sp3 and Sp4 (combined) was significantly lower than observed in studies using wild-type cells expressing these TFs." (PMID 26967243, 2016). "Over-expression of Sp1 usually means aggressive clinical behavior and much shortened overall survival in pancreatic cancer." (PMID 26041879, 2015). "The antidiabetic drug metformin decreases expression of Sp1, Sp3, Sp4 and Sp-regulated genes in pancreatic cancer cells and metformin (0–20 mM) inhibited growth of HepG2, SNU-449 and SK-Hep-1 cells after treatment for 24 and 48 hr." (PMID 26317792, 2015). "Tolfenamic acid induces proteasome-dependent downregulation of Sp1, Sp3 and Sp4 in pancreatic cancer cells." (PMID 26673922, 2015). "Metformin is an antidiabetic drug that protects patients against pancreatic cancer and metformin downregulates Sp1, Sp3, Sp4 and pro-oncogenic Sp-regulated genes in pancreatic cancer cells and tumors." (PMID 26317792, 2015). "MiR-19a expression was positively correlated with SP1 at protein levels in human pancreatic cancer and adjacent tissues." (PMID 26041879, 2015). "A recent report demonstrates that ectopic overexpression of Sp1 transcription factor renders pancreatic cancer cells more resistant to BA-mediated toxicity." (PMID 23424652, 2013). "Specificity protein 1 (Sp1) degradation by TA inhibits several cancer cell lines including pancreatic cancer cells." (PMID 22536345, 2012). "In bladder cancer cells, curcumin induced proteasome-dependent downregulation of Sp1, Sp3 and Sp4, whereas in pancreatic cancer cells this response was ROS-dependent and reversed by cotreatment with antioxidants such as GSH." (PMID 23194063, 2012). "Curcumin inhibits growth of several cancer cell lines, and studies in this laboratory in bladder and pancreatic cancer cells show that curcumin downregulates specificity protein (Sp) transcription factors Sp1, Sp3 and Sp4 and pro-oncogenic Sp-regulated genes." (PMID 23194063, 2012). "Celecoxib treatment reduces both Sp1 DNA binding affinity and its transactivating activity in pancreatic cancer." (PMID 23148884, 2012). "For instance, curcumin inhibited the proliferation of Panc28 and L3.6pL pancreatic cancer cells in vitro by down-regulating NF-kB-dependent gene transactivation and Sp1, Sp2 and Sp3 transcription factors, which are overexpressed in pancreatic cancers." (PMID 21859497, 2011). "Our study was based on previous observations describing Sp1 as an indicator of poor prognosis for pancreatic cancers." (PMID 19212434, 2009). "Therefore, the downregulation of Sp1 in pancreatic cancer results in chronic ER stress, which in turn leads to a sustained increase in cytosolic calcium, LMP, and cell death." (PMID 40723802, 2025). "Furthermore, overexpression of SP1 in pancreatic cancer cells resulted in increased expression of SAT1, which was further enhanced upon acetate treatment under low-pH conditions." (PMID 38429478, 2024). "Furthermore, Sp1 acetylation has been found to play a role in the regulation of cancers such as glioblastoma and pancreatic cancer." (PMID 39228402, 2024). "In addition, tolfenamic acid and dietary spice curcumin treatment enhanced the anti-proliferative effects in pancreatic cancer cells via suppressing SP1 expression, disrupting NF-kB translocation to the nucleus and cell cycle phase distribution." (PMID 35048778, 2022). "In pancreatic cancer, Sp1 overexpression regulates VEGF expression and angiogenesis." (PMID 32014047, 2020).
pancreatic cancer (continued). "Blockade of Sp1 has demonstrated a significant antitumor activity in pancreatic cancer." (PMID 32014047, 2020). "In this respect, NFATc2 and Sp1 seem to play a key role in the progression of pancreatic cancer." (PMID 30696421, 2019). "Therefore, here, we investigated the effect of SP1 on invasiveness and EMT in PDAC cells through LOXL2 regulation and evaluated the clinical impact of SP1 as a prognostic factor in patients with pancreatic cancer." (PMID 30976063, 2019). "However, additional studies of SP1 function and mechanism of action are required prior to practical use of SP1 for pancreatic cancer treatment." (PMID 30976063, 2019). "Ajuba/SP1 complex could form a feed forward loop to drive SP1 target gene transcription and promote cell proliferation of pancreatic cancer cells." (PMID 31101117, 2019). "Nevertheless, this study indicates that SP1 may serve as a therapeutic target for selected patients with pancreatic cancer, especially if silenced together with LOXL2." (PMID 30976063, 2019). "One possible explanation may be the activating serine-threonine-rich and glutamine-rich domains of Sp1 that increase the transcription and function of NFATc2 in pancreatic cancer." (PMID 30696421, 2019). "NFATc2 and Sp1 seem to play a key role in the progression of pancreatic cancer." (PMID 30696421, 2019). "We have previously shown that SP1 is required for ER homeostasis in pancreatic cancer." (PMID 29738634, 2018). "This was consistent with studies in this laboratory showing that CDDO-Me induced ROS and ROS-dependent downregulation of Sp1, Sp3 and Sp4 and pro-oncogenic Sp-regulated genes and has been observed with other ROS-inducing anticancer agents in pancreatic cancer cells." (PMID 29389953, 2018). "Taken together; our study added the wealth knowledge on the pro-tumoral role of FXR in pancreatic cancer and suggested that targeted inhibition of FXR and/or in combination of Sp1 might provide an alternative approach for the management of pancreatic cancer." (PMID 28402278, 2017). "Prior studies have shown that the correlated Sp1 and PLD1 had a synergic effect in promoting pancreatic cancer, which indicates that Sp1 may also be elevated and have a pro-tumoral function in osteosarcomas." (PMID 29088790, 2017). "We found previously that elevated Sp1 confers a poor prognosis for pancreatic cancer." (PMID 28402278, 2017). "In addition, we also showed that FXR was positively correlated with Sp1, a factor found to be an independent prognostic factor for pancreatic cancer in our prior study." (PMID 28402278, 2017). "When verifying the potential partner proteins Sp1 and MEF 2A (row 2 and 3) expressed in pancreatic carcinoma cells, Sp1 could also be precipitated as a binding partner of NFATc2." (PMID 28774282, 2017). "It remains unclear, however, to what extent Sp1 as a binding partner of NFATc2 has a direct influence on the transcriptional and functional activity of DNA in pancreatic carcinoma." (PMID 28774282, 2017). "Moreover, tumor growth in athymic nude mice bearing L3.6pL pancreatic cancer cells as xenografts were significantly decreased in cells depleted for Sp1, Sp3 and Sp4 (combined) or Sp1 alone." (PMID 26967243, 2016). "SP family members SP1/3/4 have been implicated as non-oncogenic addiction events in pancreatic cancer xenograft experiments." (PMID 27982060, 2016). "SP1 was found overexpressed in the same 12 human pancreatic cancer samples used for RHOB test." (PMID 26041879, 2015). "Mithramycin A and tolfenamic acid together reduce Sp1 levels in pancreatic cancer cells." (PMID 25816367, 2015). "Sp1 is a potential therapeutic target in treatment of pancreatic cancer." (PMID 26041879, 2015). "Over-expression of Sp1 was also confirmed in pancreatic cancer tissues." (PMID 26041879, 2015). "Tolfenamic acid treatment induces the degradation of Sp1, Sp3, and Sp4 in pancreatic cancer." (PMID 23148884, 2012).
pancreatic cancer (continued). "Studies in this laboratory have shown that curcumin inhibits bladder and pancreatic cancer cell and tumor growth and that the anticancer activity is due, in part, to downregulation of specificity protein (Sp) transcription factors Sp1, Sp3, Sp4 and Sp-regulated genes." (PMID 23194063, 2012). "Moreover, a key role of Sp1 in the Smad7 induction by TGFβ was recently established in pancreatic cancer cells." (PMID 21324108, 2011). "In addition, in tumors dependent on SP1, it provides insight into approaches to develop novel combination therapies that perhaps amplify the targeting of SP1, as has been described with tolfenamic acid in pancreatic cancer." (PMID 33332735, 2021). "However, it has not been determined whether chronic ER stress as a result of Sp1 downregulation leads to cell death in pancreatic cancer." (PMID 28484232, 2017). "Since activated FXR could trigger line of signaling associating with cell proliferation, metastasis and chemoresistence by phosphorylating downstream molecule, and phosphorylated Sp1 was the active form of Sp1; we postulated that the two factors were related in pancreatic cancer." (PMID 28402278, 2017). "Targeting SP1 or its downstream effector PFKFB4 effectively inhibits tumorigenesis and tumor growth in both mouse models and patient‐derived organoid models of pancreatic cancer." (PMID 40832790, 2025). "Low doses of propofol have been shown to inhibit pancreatic cancer cell proliferation, migration, and invasion by downregulating ADAM8 expression, an effect mediated by the suppression of specificity protein 1 (SP1), which regulates ADAM8 transcription." (PMID 40427200, 2025). "Transcription factor SP1 promotes tumor angiogenesis and invasion by activating VEGF expression in several tumors, such as ovarian and pancreatic cancer, following a different and independent pathway from that of TF-PAR2-VEGF." (PMID 38639888, 2024). "Given the overlap, further study regarding the crosstalk between Sp1 and STAT3 is necessary, particularly in pancreatic cancer." (PMID 38464736, 2024). "A total of 8 immune genes (ITGA7, RBM14, DENND4B, LQK1, ZNF709, COL7A1, SP1, NCBP2) were identified as independent prognostic factors of pancreatic cancer, which were used to construct a clinical predictive model." (PMID 33546693, 2021). "Other cancers in which a low miR-365 expression was observed are uterine cervical cancer through the action on SP1, prostate cancer, CRC, melanoma, pancreatic cancer." (PMID 34199293, 2021). "Our clinical data demonstrated that the overexpression of SP1 and LOXL2 correlates with poor prognosis in patients with pancreatic cancer." (PMID 30976063, 2019). "In clinical data, the co-overexpression of SP1 and LOXL2 significantly correlates with poor prognosis in patients with pancreatic cancer." (PMID 30976063, 2019). "To determine the role of Ajuba in SP1-mediated transcriptional regulation, we examined the mRNA level of the best known SP1target genes EGFR and IGF1R in pancreatic cancer Patu8988 cells used for cell growth assays by using qRT-PCR approach." (PMID 31101117, 2019). "The transcription factors Sp1, Sp3 and Sp4 are overexpressed in pancreatic cancer cells and like MALAT-1, knockdown of Sp1, Sp3 and Sp4 or Sp1/Sp3/Sp4 (combined) results in decreased cell growth, induces apoptosis, and decreases migration." (PMID 29389953, 2018). "We also show that these effects can be mediated by the activity of specificity protein 1 (SP1), a transcription factor overexpressed in pancreatic cancer." (PMID 29738634, 2018). "The data indicated that Sp1 expression was down regulated upon FXR knockdown, suggesting that the positive correlation also existed in pancreatic cancer cells in protein level." (PMID 28402278, 2017). "For example, Sp1-driven up-regulation of miR-19a decreases RHOB and promotes pancreatic cancer cell proliferation, migration and invasion." (PMID 28422727, 2017).
pancreatic cancer (continued). "In pancreatic cancer, triptolide decreases the expression and activity of O-GlcNAc transferase (OGT), which leads to inhibition of nuclear translocation of Sp1 (Specificity Protein 1) transcription factor." (PMID 28192510, 2017). "Recent reports also demonstrated that Sp1 promotes other miRNA gene expression such as miR-19a, and Sp1 was also regarded as an upstream factor of miR-19a mediated down-regulation of RHOB and promotion of pancreatic cancer." (PMID 29340098, 2017). "To further confirm the positive correlation between in Sp1 and PLD1 in PDAC, we investigated their expression and correlation in pancreatic duct epithelial (HPDE) cells and pancreatic cancer cell." (PMID 27713167, 2016). "Metformin was reported to decrease SP1/SP3 expression and their downstream targets, such as Bcl-2, survivin, and cyclin D1, in pancreatic cancer cells." (PMID 26294325, 2015). "However, RA induces thrombomodulin gene expression in pancreatic cancer cells, and this involves distal interactions of heterodimeric receptor complex with two genomic DR4 binding sites (−1531 to −1516) and Sp1 (−145 to −121) sites." (PMID 39858066, 2025). "In pancreatic cancer, the AJUBA/SP1 complex could motivate SP1 target gene transcription and promote cell proliferation." (PMID 35898403, 2022). "Jungert revealed that Smad proteins and SP1 cooperatively regulate expression of a distinct set of TGF‐β target genes potentially involved in tumour progression, including MMP‐11, cyclin D1 and Smad7 in pancreatic cancer cells." (PMID 32729205, 2020). "For this purpose, pancreatic cancer cells were transiently transfected with ‘Silencer Negative Control’-siRNA or a silencer-RNA sequence for NFATc2 or Sp1, or both." (PMID 30696421, 2019). "In pancreatic cancer, the proto-oncogene c-Fos, the tumor necrosis factor TNF-alpha, and the adhesion molecule integrin beta-3 are target genes of the interaction between Sp1 and NFATc2." (PMID 30696421, 2019). "For this purpose, the pancreatic cancer cell line PaTu 8988 t was transiently transfected with the effector plasmids of the Sp1 deletion mutants FLAG Sp1 C-terminus (zinc finger domain) and FLAG Sp1 N-terminus." (PMID 30696421, 2019). "Subsequently, we tried to investigate whether the correlation between Sp1 and FXR also exists in pancreatic cancer in protein level." (PMID 28402278, 2017). "In conclusion, our findings reveal strong expression of FXR in pancreatic cancer, and suggested that FXR may serve as an oncogenic factor that promotes pancreatic progression by collaborating with Sp1." (PMID 28402278, 2017). "We further show that inhibition of Sp1, as well as induction of ER stress, leads to lysosomal membrane permeabilization (LMP), a sustained accumulation of cytosolic calcium, and eventually cell death in pancreatic cancer." (PMID 28484232, 2017). "Combination therapy targeting SP1 and PFKFB4 demonstrates significant efficacy in pancreatic cancer models in vivo, without observable toxicity." (PMID 40832790, 2025). "Based on in vitro studies on pancreatic cancer cells (MIA PaCa-2) and in vivo studies on athymic nude mice treated with the same cells, it was found that, after Sp1 silencing and the induction of stress via TM, Sp1 does not bind to the Grp78 promoter." (PMID 40723802, 2025). "Third, MACC1 is not the only regulator of MET, and there are many proteins other than MACC1 that can directly regulate MET expression (e.g., HIF1, SP1, AP1, and Ets-1), suggesting that MACC1 may not be a predominant regulator of MET in pancreatic cancer." (PMID 36333284, 2022).
colorectal cancer (84 papers, 2007 to 2025). A primary or metastatic malignant neoplasm that affects the colon or rectum. "The allele G was previously associated with reduced apoptosis of colorectal cancer cells because it affects the coupled binding of transcription factors SP1 and STAT1 to chromatin, altering complex recruitment for transcriptional activation." (PMID 37798436, 2023). "Moreover, elevated miR-375 is found to inhibit the invasion and metastasis, and regulate epithelial-mesenchymal transition-associated genes of colorectal cancer via inhibiting SP1." (PMID 31927536, 2020). "Moreover, we conducted rescue assays to determine whether Sp1 was involved in the MIER3 silencing-associated increases in colorectal cancer cell proliferation and invasion." (PMID 28887525, 2017). "Previous studies have shown that it inhibits proliferation and invasion in cervical cancer by targeting specificity protein 1 (Sp1) and also inhibits colorectal cancer production by interacting with the KRAS/AKT/ERK pathway." (PMID 39595529, 2024). "Collectively, Qc acts in a dual mode and exerts its effects by counteracting Sp1 in colorectal cancer." (PMID 37627542, 2023). "In accordance, luciferase assay demonstrated genetic manipulation of Sp1 alters STC2 promoter-mediated luciferase activity in a dose-dependent manner in colorectal cancer cells." (PMID 35501821, 2022). "Sp1 is upregulated in several human cancers like colorectal cancer, and the expression of Sp1 is correlated with poor prognosis." (PMID 35501821, 2022). "Of note, this inhibitor of DNA-to-RNA transcription has been reported to target colorectal cancer stem cells, perhaps due to the inhibition of the transcription factor Sp1." (PMID 34675191, 2021). "Butyrate diminishes the recruitment of Sp1 to the NRP1 promoter in colorectal cancer, whereas the effect of TSA on NRP1 expression in endothelial cells is mediated by semaphorine III." (PMID 34635175, 2021). "Co-transfection of an SP1 expression vector with reporter constructs markedly increased luciferase activity in colorectal cancer cells." (PMID 34685502, 2021). "For example, restoring expression of miR-7-5p suppressed tumorigenesis in colorectal cancer cells and reversed by SP1-induced lncRNA TINCR, and miR-7-5p was a potential biomarker in neuroendocrine neoplasms of the small intestine." (PMID 32962742, 2020). "Consistent with this, one study showed that silencing of SP1 inhibited growth and migration and attenuated the effect of miR‐382 inhibitor on colorectal cancer cell behaviors (Ren, Zhang & Jiang, 2018)." (PMID 31823440, 2020). "Overall, above results indicate that SNHG1 overexpression in colorectal cancer is at least partly due to SP1 activation." (PMID 30266084, 2018). "ZEB2 expression was significantly correlated with Sp1 expression in human colorectal cancers (n = 244, r = 0.200, P = 0.00166 and n = 382, r = 0.166, P = 0.00113 for TCGA, Nature 2012, and TCGA, Provisional, studies, respectively)." (PMID 29416649, 2018). "Sp1, a member of the transcription factor family, plays an important role in colorectal cancer development and progression." (PMID 28422727, 2017). "Thirdly, our study demonstrated for the first time that miR-22/Sp1 network inhibits PTEN/AKT pathway in colorectal cancer." (PMID 28422727, 2017). "It has been shown that Sp1 acts as a tumor suppressor to suppress colorectal cancer growth and metastasis by increasing miRNA‐52d‐5p transcription for target CTHRC1." (PMID 28846829, 2017). "Sp1-mediated microRNA-520d-5p suppresses tumor growth and metastasis in colorectal cancer by targeting CTHRC1." (PMID 28422727, 2017). "In conclusion, we demonstrated that atmospheric-pressure dielectric barrier plasma induced apoptosis and cell-cycle arrest, accompanied by the downregulation of Sp1 expression, in two human colorectal cancer cell lines, HT29 and HCT116." (PMID 28225083, 2017).